IL1B (interleukin 1 beta)
Diseases named in the same sentence as IL1B in open-access papers (continued):
Sharing a sentence is not in itself a finding about the gene and the disease.
Hypoglycemia (22 papers, 2011 to 2025). A decreased concentration of glucose in the blood. "In contrast, in obese db/db mice with T2DM injection of recombinant IL-1β can cause long-lasting hypoglycemia in db/db mice." (PMID 31191559, 2019). "Fasted mice were protected from IL-1β-induced weight-loss, hypoglycemia, loss of locomotor, and social anxiety." (PMID 25071776, 2014). "Two studies claimed that Irak4 (Interleukin-1 receptor associated kinase-4) controls hypoglycemia-induced glucagon secretion by modulating hypothalamic Il-1β signaling, and Agpat5 activation in AgRP (agouti-related protein) neurons leads to hypoglycemia-induced glucagon secretion." (PMID 37764697, 2023). "We confirmed that Irak4, by modulating hypothalamic Il-1β signaling, indeed controls hypoglycemia-induced glucagon secretion." (PMID 36180454, 2022). "First, physiological parameters including blood glucose, SpO2, and IL-1β levels for the exclusion of probable diseases of respiratory depression, infection, or hypoglycemia were screened in the mice enrolled in this study." (PMID 34611079, 2021). "Here, we show that both LPS and interleukin (IL)-1β trigger hypoglycemia, reduce CSF glucose, and suppress spontaneous activity." (PMID 32513828, 2020). "Although IL-1β-induced hypoglycemia was prevented in IL-1R1−/− mice, LPS-induced reductions in glucose were statistically indistinguishable from those in WTs." (PMID 32513828, 2020). "We demonstrated that the expression of TNF-α, IL-1β, and IL-6 was increased following acute severe hypoglycemia." (PMID 29793504, 2018). "At the experimental level IL-1β is known to produce a profound hypoglycemia in mice and a re-setting of glucose homeostasis that favors fuel re-distribution towards immune cells but with a paradoxical reduction of food intake." (PMID 22022605, 2011). "Following hypoglycemia, transient changes from baseline occurred in DKK1, cathepsin A, cathepsin G, cathepsin H, cathepsin S, cathepsin Z, parathyroid hormone (PTH), Sphingosine kinase 1 and 2 (SPK1/2), and interleukin-1 beta (IL1 beta) over the post-hypoglycaemia time course." (PMID 41373586, 2025). "To test whether IL-1β is necessary for LPS-induced hypoglycemia, we administered LPS (250 μg/kg, i.p.)and IL-1β (25 μg/kg, i.p.)to IL-1 receptor-1 knock-out (IL-1R1−/−) mice and c57BL/6J wild-type (WT) controls." (PMID 32513828, 2020). "IL-1β antagonism with IL-1RA has been reported to attenuate LPS-induced hypoglycemia." (PMID 32513828, 2020). "We investigated the contribution of IL-1β signaling to LPS-induced hypoglycemia." (PMID 32513828, 2020). "This suggested that suppression of PPAR-γ expression may be involved in the high levels of TNF-α, IL-1β, and IL-6 induced by hypoglycemia." (PMID 29793504, 2018). "On the other hand, TNF-α and IL-1β have been demonstrated to induce hypoglycemia." (PMID 28836970, 2017). "Among these three concentrations, 25% PF127 gel formulation was found to be the best one that prolonged the in vitro and in vivo release, showed greater efficacy to induce hypoglycemia and inhibited IL-1β-stimulated production of IL-6 in wistar rats when compared with that of IL-1Ra solution." (PMID 23409091, 2013). "Therefore, while IL-1β might be a key mediator of hypoglycemia at 25 μg/kg LPS, IL-1RA barely limits hypoglycemia with LPS at 250 μg/kg (current study)." (PMID 32513828, 2020). "Furthermore, plasma glucose levels correlated negatively with brain levels of mRNAs encoding TNF-α, IL-1β, IL-6, CCL2 and iNOS, suggesting that hypoglycemia and the expression of these pro-inflammatory markers might be linked." (PMID 30375380, 2018). "It is well known that hypoglycemia-induced release of proinflammatory factors, including TNF-α, IL-1β, and IL-6, plays a critical role in BBB damage." (PMID 29793504, 2018).
Hypoglycemia (continued). "Hypoglycaemia caused a significant increase in LPS- or P3C-stimulated TNF-α and IL-1β production and a decrease in stimulated IL-10 production, which normalised after 24 h and none of which was modified by antecedent hypoglycaemia." (PMID 38331900, 2024). "Interestingly, IL-1β and MCP-1 expression in macrophages cultured under hypoglycemia compared with their expression in the normoglycemic controls, respectively (p > 0.05)." (PMID 32806763, 2020). "To determine whether the effect of AQP4 deletion on BBB disruption after hypoglycemia is involved in the immunomodulatory influence of AQP4 deletion, we examined TNF-α, IL-1β, and IL-6 mRNA expression in the brains of mice." (PMID 29793504, 2018).
nasopharyngeal carcinoma (22 papers, 2012 to 2025). A carcinoma arising from the nasopharyngeal epithelium. "In Epstein–Barr virus (EBV)-associated nasopharyngeal carcinoma, viral DNA and intra-tumor DAMPs stimulate inflammasomes to produce IL-1β." (PMID 32635472, 2020). "Furthermore, it has been shown that the autophagy-dependent secretion of IL-1β by the AIM2 inflammasome requires the microtubule associated protein EB1 in nasopharyngeal carcinoma and monocyte cell lines." (PMID 29750813, 2018). "Nasopharyngeal carcinoma (NPC) is a neoplasm related to inflammation; the expression of cytokines, such as CCL3, CCL4, CCL20, IL-1α, IL-1β, IL-6, IL-8, and IL-10, among others, is presumed to be associated with NPC occurrence and development." (PMID 39483474, 2024). "In nasopharyngeal carcinoma triggered by EBV infection, EBV-encoded latent membrane protein 1 directly interacted with the glycolytic protein Glut1 to induce NLRP3 and IL-1β expression in myeloid-derived suppressor cells." (PMID 40041420, 2025). "In nasopharyngeal carcinoma, immunohistochemical analysis revealed that patients with upregulated IL-1β expression had better local recurrence-free and disease-free survival." (PMID 40244135, 2025). "Recent studies confirmed that tumor cell-derived IL-1β increases the survival rate of EB virus-induced nasopharyngeal carcinoma via recruiting concentrated granulocytes." (PMID 31754923, 2019). "The maturation of IL-1β by an activated inflammasome is an important mechanism for tumor pathogenesis in melanoma, colorectal cancer, and nasopharyngeal carcinoma (NPC)." (PMID 27367024, 2016). "Induction of IL‐1β release in nasopharyngeal carcinoma potently enhances antitumor effects." (PMID 41025546, 2025). "High levels of IL-1β were also observed in nasopharyngeal carcinoma (NPC) cases." (PMID 40568785, 2025). "IL-1β is also elevated in the EBV-positive nasopharyngeal carcinoma." (PMID 36675141, 2023). "Both IL-1β and IL-8 have been found elevated in EBV-positive nasopharyngeal carcinoma (NPC), and polymorphisms in IL-1β correlate with the risk of this disease in endemic regions." (PMID 36014102, 2022). "Studies have revealed that IL-1β/IL-18 can induce T and NK cell activation and killing and that IL-1β recruits neutrophils to control tumor growth and prolong survival in EBV-induced nasopharyngeal carcinoma model animals." (PMID 40982560, 2025). "Nasopharyngeal carcinoma cells infected with EBV and treated with PDT significantly increased IL-8, IL-1α, and IL-1β levels, resulting in cell death." (PMID 37239013, 2023). "Nasopharyngeal carcinoma cells treated with PDT showed that IL-8, IL-1α, IL-1β, LC3BI, LC3BII, MMP2, and MMP9 levels were significantly higher than in groups that did not receive PDT." (PMID 37239013, 2023). "In this concept, immunohistochemical analyses showed that upregulation of ASC, caspase-1, IL-1β, AIM2, RIG-I, and NLRP3 expression correlated with better local recurrence-free survival and disease-free survival of nasopharyngeal carcinoma patients." (PMID 32635472, 2020). "PDT also increased IL-1α and IL-1β levels in nasopharyngeal carcinoma cells without EBV infection, but at a lower rate than tumors infected with EBV." (PMID 37239013, 2023). "In nasopharyngeal carcinoma (NPC), AIM2-induced IL-1β in tumor cells plays a crucial role in tumor control by recruiting neutrophils." (PMID 36386141, 2022). "This promotes the induction of GM-CSF, IL-6, and IL-1β production through COX-2 and NLRP3 inflammasome signaling pathways to enhance MDSCs differentiation and expansion, thereby promoting nasopharyngeal carcinoma (NPC) progression." (PMID 31275326, 2019).
Neonatal sepsis (22 papers, 2007 to 2025). Systemic inflammatory response to infection in newborn babies. "IL-1β is a potent pro-inflammatory cytokine and a key driver underlying impaired outcomes associated with autoinflammatory disorders and neonatal sepsis." (PMID 39000127, 2024). "A strong clinical association between IL-1β-mediated inflammation and neonatal sepsis has been widely reported in the literature." (PMID 36769133, 2023). "In neonatal sepsis, plasma, serum and cerebrospinal fluid (CSF) IL-1β were elevated in infants at a greater risk of neurological impairment." (PMID 36769133, 2023). "Although IL-1β has been implicated during neonatal sepsis, less is known about IL-1α in human neonates." (PMID 32479514, 2020). "Three cytokines, IL-6, TNF-α, and IL-1β, were investigated and strongly implicated as diagnostic tools in neonatal sepsis." (PMID 28487810, 2017). "The diagnostic value of IL-6, TNF-α, and IL-1β is limited by the time of blood sample collection, which should be as early as possible if neonatal sepsis is suspected, since these cytokines have very short half-life." (PMID 25614712, 2014). "Neonatal sepsis is a pathological condition associated with elevated levels of pro-inflammatory cytokines, including IL-1β, TNF-α, and IL-6." (PMID 22114550, 2011). "Our study further demonstrated that by inhibiting IL-1β production in the brain, neurodevelopment could be improved, which indicated that IL-1β could be a potential therapeutic target against neurodevelopment impairment caused by neonatal sepsis." (PMID 37834141, 2023). "Elevated serum levels of several pro-inflammatory cytokines—such as IL-6, IL-8, IL-10, IL-1β, TNF-α, and MCP-1—have been associated with neonatal sepsis." (PMID 40948499, 2025). "This research indicated that sustained activation of necroptosis via IL-1β contributed to long-term cognitive dysfunction after neonatal sepsis." (PMID 37834141, 2023). "In the present study, we demonstrated that neonatal sepsis led to sustained neuroinflammation, characterized by elevated levels of IL-1β." (PMID 37834141, 2023). "In the present study, serum levels of the proinflammatory cytokines TNF-α, IL1-β, and IL-6 and the anti-inflammatory cytokines IL-4 and IL-10 were evaluated for 25 subjects with neonatal sepsis." (PMID 28367457, 2017). "However, in contrast to TNF-α and IL-6, IL-1β serum levels are extremely low (<50 pg/mL) during neonatal sepsis." (PMID 38562936, 2024). "Furthermore, the potential reciprocal activation between IL-1β and RIP1 could be the leading cause of sustained neuroinflammation after neonatal sepsis, which warrants further investigation." (PMID 37834141, 2023). "The results indicate that the inflammatory mediators IL-1β, IL-6, IL-8, and TNF-α can be used to diagnose and assess the therapeutic efficacy of neonatal sepsis." (PMID 31671729, 2019). "For instance, tumor necrosis factor alpha (TNF-α), interleukin-1-beta (IL-1β), interleukin-6 (IL-6), and CXCL8 (interleukin-8) levels become rapidly and substantially increased during neonatal sepsis." (PMID 28367457, 2017). "Serum levels of IL-1β, IL-6, IL-8, and TNF-αare mediators of inflammation and can be used at the diagnosis and at theevaluation of the therapeutic efficiency in neonatal sepsis." (PMID 18274637, 2007). "GNT treatment decreased LPS-induced elevation of TNF-α, IL-2, and IL-1β expression levels and increased LPS-induced elevation of IL-10 expression levels in the peritoneal fluid, indicating the anti-inflammatory effect of GNT in neonatal sepsis." (PMID 36162982, 2022). "The study identified that IL-1α, and not IL-1β, was responsible for IL-1R1-dependent lethality during neonatal sepsis." (PMID 32479514, 2020). "In cases of neonatal sepsis, Fan and Yu (2012) did not recommend the isolated use of inflammatory markers CRP, PCT, interleukin-8 (IL-8), TNF-α and interleukin-1 beta (IL-1β); although IL-6 was rated as superior in relation to the majority of markers, it should not be used in isolation." (PMID 34846061, 2022).
pancreatic ductal adenocarcinoma (22 papers, 2017 to 2025). An infiltrating adenocarcinoma that arises from the epithelial cells of the pancreas. "While, in pancreatic ductal adenocarcinoma, TREM2 deficiency promotes tumor progression through the expansion of proinflammatory macrophages and IL-1β–driven pathogenic inflammation." (PMID 41253786, 2025). "The latest report suggests that TAM and tumor monocytes are the main sources of IL-1β in human pancreatic ductal adenocarcinoma, which is closely related to the malignant progression of human pancreatic ductal adenocarcinoma and the poor prognosis of patients." (PMID 38762529, 2024). "In the context of pancreatic ductal adenocarcinoma, M2-type macrophages, stimulated by tumor inflammation and Ig-G, release IL-1β, which not only promotes the EMT phenotype but also increases metastatic potential." (PMID 39068459, 2024). "Penny and colleagues also reported that pancreatic ductal adenocarcinoma produced TAMs expressing both M1 (IL‐1β, IL6, and TNF‐α) and M2 (CD163, CD206, and Arg1) markers." (PMID 37688511, 2023). "IL-1β promotes stemness of tumor cells, supporting the early finding that IL-1β–mediated tumor-stroma interactions confer chemoresistance in pancreatic ductal carcinoma cells through a paracrine effect." (PMID 36264639, 2022). "IL-1β signaling in tumor cells recruits monocytes, triggering the IL-1β + TAM state that drives inflammatory reprogramming in neighboring pancreatic ductal adenocarcinoma cells, enhancing synthesis of PGE2, TNF, and other factors that perpetuate the IL-1β + TAM state." (PMID 39068459, 2024). "In fact, in pancreatic ductal adenocarcinoma, interleukin 1 beta (IL-1β) secretion from immune cells has emerged to be a potential initiator of nuclear factor kappa-light-chain-enhancer of activated B cells (NF-kB) signaling in fibroblasts, instructing them to produce a pro-tumorigenic secretome." (PMID 35892828, 2022). "Indeed, Penny and colleagues also reported that pancreatic ductal adenocarcinoma-generated TAMs expressed both M1 (IL-1β, IL6, and TNF-α) and M2 (CD163, CD206 and Arg1) markers." (PMID 30927925, 2019). "Furthermore, IL1β + TAMs, a subset of macrophages in pancreatic ductal adenocarcinoma, have been identified and analyzed for their transcriptomic profile, which revealed their primary functions in promoting inflammatory responses, leukocyte recruitment, and angiogenic effects." (PMID 39068459, 2024). "Another study showed the upregulation of IL-6, IL-1b and VEGF in pancreatic ductal adenocarcinomas in the presence of high concentrations of G-CSF." (PMID 35022523, 2022). "IL-1β induces KIAA1199 expression and migration in pancreatic ductal adenocarcinoma cells." (PMID 37569797, 2023).
Parkinson’s (22 papers, 2012 to 2025). "Studies in PD patients show evidence of augmented levels of potent pro-inflammatory molecules e.g., TNF-α, iNOS, IL-1β whereas in experimental Parkinsonism it has been consistently demonstrated that dopaminergic neurons are particularly vulnerable to activated glia releasing these toxic factors." (PMID 25883554, 2015).
pulmonary edema (22 papers, 2006 to 2025). Accumulation of fluid in the lung tissues causing disturbance of the gas exchange that may lead to respiratory failure. "Proinflammatory cytokines such as IL-6, TNF-α, and IL-1β were found to be associated with brainstem encephalitis complicated by pulmonary edema in EV-A71 infections." (PMID 40377310, 2025). "In addition, the increase of the ratio of W/D weight as a key indicator of the severity of pulmonary edema and the pro-inflammatory factor levels of IL-1β, IL-6, and TNF-α caused by PQ was reverted back by Andro." (PMID 37275765, 2023). "A microarray analysis on ARDS-associated pulmonary edema indicated a prominent role for IL-1β." (PMID 24696530, 2014). "Fat embolism significantly increased pulmonary NLRP3 expression, lipid peroxidation, IL-1β release, and macrophage infiltration within four hours, accompanied by severe pulmonary edema." (PMID 40806699, 2025). "In these studies, SEV significantly improved the oxygenation of lung grafts and reduced pulmonary edema through the reduction of IL-1β, IL-6, and TNF-α." (PMID 33506025, 2021). "The main findings of this study are that VILI is associated with pulmonary edema, increased levels of BALF inflammatory cytokines IL-1β, IL-6, and RANTES, neutrophil counts, MPO activity, lung Rho activation, and ultrastructural damage of alveolar endothelium." (PMID 25019086, 2014). "In vivo study revealed that DHK attenuated wet/dry weight ratio of lung tissue, lung neutrophil intrusions and pulmonary oedema, and reduced the increased total cells, neutrophils, TNFα and IL1β expression in bronchoalveolar lavage fluid (BALF) in LPS‐stimulated BALB/c mice." (PMID 40857065, 2025). "In addition, the excessive release of IL-1β can increase the permeability of alveolar epithelial and vascular endothelial cells, which will lead to pulmonary edema." (PMID 34787801, 2022). "IL-1β is responsible for the severe manifestations of envenomation, such as pulmonary edema." (PMID 32150895, 2020). "By inhibiting NF-κB–dependent transcription of pro-inflammatory cytokines (TNF-α, IL-1β, IL-6) and attenuating oxidative stress, deslanoside may help preserve alveolar–capillary barrier integrity, reduce endothelial permeability, and alleviate pulmonary edema." (PMID 41244837, 2025). "Inhibits neuraminidase activity, reduces lung index, alleviates pulmonary edema, reduces inflammatory factors TNF-α, IL-1β, increases PI3K protein expression, and reduces the protein expression of p-Akt, caspase-3 and NF-κB." (PMID 33192523, 2020). "Reduced lung inflammation and pulmonary edema.Reduced MPO activity and IL-1β level.Increased IL-10 level." (PMID 32519302, 2020). "Previously published data have demonstrated in cases of high-altitude pulmonary edema, there is an increase in the infiltration of inflammatory cells, specifically macrophages and neutrophils, as well as elevated levels of cytokines such as IL-6, TNF-α, and IL-1β." (PMID 38166725, 2024). "One study indicated that patients with brainstem encephalitis and pulmonary edema exhibit elevated serum and CSF levels of IL-6, TNF-α, IL-1β, and IFN-γ, suggesting that pulmonary edema may result from increased vascular permeability due to systemic inflammation." (PMID 39767680, 2024).